IL22 (interleukin 22)
Diseases named in the same sentence as IL22 in open-access papers (continued):
Sharing a sentence is not in itself a finding about the gene and the disease.
inflammation (continued). "They found that epicutaneous sensitization with ovalbumin in mice further challenged with intranasal ovalbumin led to increased expression of IL-22 in serum and lungs, which was associated with enhanced AHR and mixed neutrophilic and eosinophilic airway inflammation." (PMID 35386663, 2022). "That is why we examined the inflammatory role of IL-22 on brain inflammation in this study." (PMID 35054942, 2022). "To explore the potential mechanisms of IL-22 which inhibited the OVA-induced airway inflammation, we performed immunohistochemistry to detect the expression of functional IL-22 receptor, a heterodimer of IL-22RA1 and IL-10RB, and its soluble binding protein, IL-22BP." (PMID 34836520, 2021). "However, we found increased numbers of innate lymphocyte as the main source of IL-22 production during the development of allergen specific airway inflammation in the lung." (PMID 21789181, 2011). "In addition, IL‐22 might control the extent of IFN‐γ‐mediated lung inflammation and therefore play a tissue‐restricted regulatory role." (PMID 39073027, 2024). "However, the deficiency of IL-22 neither affects pulmonary inflammation nor neutrophil or eosinophil frequencies." (PMID 37445595, 2023). "Hence, a protective action of IL-22 on airway allergic inflammation, in particular on airway eosinophilic inflammation and Th2 cytokine production, on AHR and even on some pathological feature of airway remodeling (goblet cell hyperplasia) has been described in several studies." (PMID 35386663, 2022). "IL-22 is protective against this hypervirulent strain Mtb HN878 in mice and reduces the severity of lung inflammation and neutrophil-mediated lung epithelial cell injury by inducing the expression of anti-apoptotic proteins Bcl2 and Mcl1 and enhancing the production of antimicrobial peptides." (PMID 33718260, 2021). "Additionally, since Irgm1-/- mice were not deficient in key host defense cytokines (IL-22, Reg3γ and Reg3β), the results further suggest that C. rodentium outgrowth and mortality of Irgm1-/- mice cannot be explained by “general susceptibility” to intestinal inflammation." (PMID 32453761, 2020). "We have recently found that PGE2 promotes IL-22 production from both T cells and ILC3s.7 8 In this study, we have investigated the hypothesis that PGE2 inhibits acute lung neutrophilic inflammation through modulating lung ILC3 production of IL-22." (PMID 29574419, 2018). "In cell differential counts, OVA stimulated Tg(−) group (OVA/Tg(−)) showed substantial eosinophilic airway inflammation, while the number of eosinophils in the BAL of OVA treated IL-22 Tg(+) (OVA/Tg(+)) group was significantly less compared to the OVA/Tg(−) group." (PMID 25254361, 2014). "Although ILCs provide a rapid source of IL-22 that is essential for early protection of epithelial barrier function upon inflammatory insult, CD4+ T cells become the dominant source of IL-22 in the intestinal lamina propria (LP) during chronic intestinal inflammation." (PMID 32901017, 2020).
metabolic disorders (38 papers, 2015 to 2026). "We have presented preclinical evidence showing that RYGB weight-loss independently induces gut Il-22 release in association with improvements in glycemic control, providing further support for the use of this cytokine to treat metabolic disease." (PMID 36992680, 2023). "IL-22 signaling is shown to suppress metabolic disorders, as IL-22 administration to obese db/db leptin receptor-deficient mice reversed many of the observed metabolic symptoms." (PMID 33562334, 2021). "As previously reported, the induction of IL-22 in innate lymphoid cells and CD4+T cells is impaired in obese mice, and IL-22 deficiency in mice has shown that mice are prone to developing metabolic disorders." (PMID 31118952, 2019). "Therefore, we need more clinical studies and observations to confirm the alterations in IL-22 levels in patients with PCOS, as well as more effort to investigate the underlying mechanisms of the differences in IL-22 levels among various metabolic diseases." (PMID 37525285, 2023). "The increased gut abundance of ILC1s (and T-bet+ ILC3 cells) was related to the reduction of IL-22 and the exacerbation of metabolic disease in a DIO murine model." (PMID 40328980, 2025). "It is important to note that previous studies evaluating the role of IL-22 in mediating metabolic disorders have relied solely on the use of global knockouts of the cytokine or its receptor or systemic treatment and/or depletion of IL-22." (PMID 38383607, 2024). "While studies have indicated a beneficial role for IL-22 in ameliorating the onset of metabolic disorders, key questions remain." (PMID 38383607, 2024). "In the early stages of metabolic diseases, serum IL-17/IL-22 levels decrease along with changes in the gut microbiome." (PMID 39211822, 2024). "Recently, a cytokine called interleukin-22 (IL-22) has aroused attention by virtue of its advantages in multiple models of metabolic diseases." (PMID 37525285, 2023). "Recently, interleukin-22 (IL-22) has been shown to be therapeutically effective in immunological dysfunction and metabolic diseases, which suggests a role in the treatment of PCOS." (PMID 37525285, 2023). "In fact, the role of the cytokine IL-22 in maintaining integrity of the intestinal barrier with attenuated metabolic disorders was demonstrated." (PMID 33292434, 2020). "Our study demonstrates that IL-22 and ILC3s play an important role in mucosal defense and controlling the metabolic disorder in T2DM mice infected with Mtb." (PMID 31809521, 2019). "Due to its unique role in alleviating metabolic disorders and its direct restorative effect on pancreatic beta-cells, IL-22 constitutes an important factor potentially mediating post-surgery anti-diabetic and beneficial metabolic effects." (PMID 30639417, 2019). "Among its multiple positive influences on metabolic disease, IL-22 injection in obese mice leads to increased serum PYY levels which is thought to contribute to the reduction in food intake and weight." (PMID 30639417, 2019). "IL-22 is an inflammatory mediator of the innate and adaptive immune response which also regulates adiposity and metabolic disorders." (PMID 30639417, 2019). "The benefit effect of IL-22 in metabolism opens new avenues for novel therapy of metabolic diseases, however, the mechanism by which IL-22 alleviates oxidative and ER stress in pancreatic islets has not been definitively elucidated." (PMID 26784895, 2016). "A recent study shows that IL22, a cytokine that maintains gut mucosal barrier integrity within the intestine, alleviates metabolic disorders and restores mucosal immunity." (PMID 27123997, 2016). "Hitherto, it has become apparent that IL-22 ameliorates pancreatic β-cell stress and metabolic disease in murine obesity." (PMID 26793108, 2015). "ILC3s-derived IL-22 can enhance the intestinal mucosal barrier function, reduce endotoxemia and inflammation, ameliorate insulin sensitivity, and improve the metabolic disorder of polycystic ovary syndrome." (PMID 38536726, 2024).
metabolic disorders (continued). "Overall, the fact that IL-22 from ILC3s regulates metabolism homeostasis highlights the link between metabolism and immunity and provides a new avenue for therapeutic intervention of metabolic diseases." (PMID 35574038, 2022). "Furthermore, CB0313.1 increased colon IL-22 expression, which has a beneficial effect on colon barrier integrity and metabolic disorders." (PMID 27123997, 2016). "In this study, whether there are different expressions of IL-1β, IL-18, and IL-22, which had been reported to be involved in metabolic disorder and insulin sensitivity, is interesting but yet investigated." (PMID 26681840, 2015). "Thus, Il-22 is a potential novel treatment for metabolic disease." (PMID 36992680, 2023). "Notably, IL-22 from ILC3s has been demonstrated to improve metabolic disorders." (PMID 35574038, 2022). "Although the modulation of systemic metabolic disorders and inflammation is crucial for PCOS patients, we should also investigate deeper into how IL-22 will regulate other typical phenotypes of PCOS." (PMID 37525285, 2023). "To better develop novel treatment models, we require additional clinical data and fundamental research to comprehend the alterations and mechanisms of IL-22 in PCOS and other metabolic diseases." (PMID 37525285, 2023). "The roles of IL-22 in metabolic regulation opens new avenues for its potential application in NAFLD and other metabolic disorders." (PMID 34944732, 2021). "Unlike other cytokines, interleukin-22 (IL-22), a small cytokine mainly produced by Th1, Th17, Th22 and ILC3 cells, has been shown to alleviate metabolic disorders in mice and protect pancreatic islet properties beyond its immunological functions." (PMID 30639417, 2019). "In contrast to IL-22-Fc, anti-FGFR1 antibody failed to stimulate the wound healing process in db/db mice despite lowering serum glucose, suggesting that improvement of metabolic disorders alone is not sufficient to promote wound healing in this model." (PMID 28125663, 2017).
infectious disease (30 papers, 2010 to 2025). A disorder directly resulting from the presence and activity of a microbial, viral, or parasitic agent in humans. "This suggests the need for more research on the underlying mechanisms of Th22/IL-22 in infectious diseases." (PMID 36839448, 2023). "IL-22 is a member of the IL-10-related cytokine family, and has been implicated in both chronic inflammatory diseases and infectious diseases." (PMID 22952908, 2012). "IL-22 is an important Th17 T-cell-associated cytokine that mediates tissue responses during inflammation, but it also has a role in the host response to infectious diseases." (PMID 20211031, 2010). "This resistance to infectious diseases is associated with the overexpression of IL-22." (PMID 29318122, 2018). "IL-22 contributes to both chronic inflammatory and infectious diseases, and may have protective or pathogenic effects, depending on the tissue and disease state." (PMID 28139719, 2017). "IL-22 is a member of the IL-10 family and plays a crucial role in a range of inflammatory and infectious diseases." (PMID 39201060, 2024). "Given the complexity of Th22/IL-22 downstream signaling pathways, further exploration of the role and mechanisms of Th22 cells in infectious diseases is still needed." (PMID 36839448, 2023). "Since it is unreasonable to apply the conclusions of animal experiments directly to human beings, there is currently very limited knowledge about how Th22/IL-22 plays a role in human infectious diseases." (PMID 36839448, 2023). "In summary, based on the available studies, we have characterized in detail the roles and mechanisms of Th22 cells and IL-22 in infectious diseases." (PMID 36839448, 2023). "Herein, we review the current understanding of Th22 cells, including their definition, differentiation and mechanisms, and the effect of Th22/IL-22 on human infectious diseases." (PMID 36839448, 2023). "The role of IL-22 in the pathogenesis of autoimmune and infectious diseases, as well as in malignancies, has been extensively studied." (PMID 36366333, 2022). "By applying this perspective to the literature, we hope to promote further research on the role of IL-22 in shaping adaptive immunity in inflammatory and infectious diseases." (PMID 33692792, 2021). "IL-22 is a pleiotropic cytokine with pro and anti-inflammatory properties and plays contrasting functions in diverse inflammatory or infectious diseases." (PMID 32517114, 2020). "Regardless, pre-clinical animal models suggest that IL-22 has significant therapeutic potential in the context of infectious diseases." (PMID 32582219, 2020). "IL-22, a member of the IL-10 family or IL-10 superfamily, plays an important role in various inflammatory diseases and infectious diseases." (PMID 28030850, 2017). "The impact of IL-17 and IL-22 on numerous infectious diseases of the skin and mucosa have been described." (PMID 30402605, 2017). "IL‐22 is involved in the host response to infectious diseases by promoting inflammation but, reflecting its tissue repair properties, it exerts both pro‐ and antiinflammatory actions in allergic and autoimmune inflammatory disorders." (PMID 24497523, 2014). "The role of IL-22 in inflammatory and infectious diseases varies with tissue and disease conditions." (PMID 22952908, 2012). "Our review also summarized recent advances in Th22/IL-22-targeted therapies, which may provide promising insights for infectious disease treatment." (PMID 36839448, 2023). "Interestingly, STAT3 and the antimicrobial protein calgranulin A can be both protective and deleterious in the Th22/IL-22 axis, depending on the type of infectious disease." (PMID 36839448, 2023). "In summary, studies have confirmed the therapeutic effect of Th22/IL-22 on infectious diseases." (PMID 36839448, 2023). "IL-22BP allows for more exquisite regulation of a cytokine and may be key to harnessing IL-22 biology to combat chronic inflammatory and infectious diseases." (PMID 34868019, 2021).
infectious disease (continued). "Interleukin-22 (IL-22) is a crucial cytokine for regulating host immunity in infectious diseases." (PMID 32843067, 2020). "Less is known with regard to human IL-22 production and signaling in human infectious diseases." (PMID 32582219, 2020). "The role of IL-22 in inflammatory and infectious diseases depends on the tissue and the disease." (PMID 28139719, 2017). "However, in another context in which different infectious diseases and other cytokines were specifically evaluated IL-22−/− mice were resistant to mycobacterial infection." (PMID 23460846, 2013). "In addition to inflammation induced by autoimmune or infectious diseases, IL-22 also plays a role in fibrosis after wounding." (PMID 22312190, 2012). "Th22 cells, known to promote neutrophil mobilization and activation through cytokine secretion (IL-22 and TNF-α), play a crucial regulatory role in autoimmune and infectious diseases." (PMID 39039547, 2024).
intestinal disease (18 papers, 2011 to 2025). "AHR-/- mice exhibit significant RAR-related orphan receptor γt+ (RORγt) ILC deficiency, leading to a decrease in IL-22 production and poor protection against intestinal bacterial infections." (PMID 37063879, 2023). "Special interest has developed in the use of IL-22 in therapy for intestinal diseases such as GVHD and IBD." (PMID 32582668, 2020). "As A20ZF7 mouse small intestines contain dramatic expansions of SILP Th17 cells and increased tissue-wide expression of IL-17A and IL-22, we next sought to functionally define the potential roles of these cytokines in regulating intestinal disease in A20ZF7 mice." (PMID 40892518, 2025). "In conclusion, IL-22 plays an important role in the pathogenesis of many intestinal diseases." (PMID 26793707, 2015). "Therefore it is important to understand the activating factors and molecular pathways controlling IL-17 and IL-22 production as this will eventually lead to the development of improved treatments for intestinal disease." (PMID 23508190, 2013). "In intestinal diseases, IL-12 elicits ILC1s to switch into ILC3s, whereas IL-1 plus IL-12 collaboratively induces ILC2s to convert into ILC1s in respiratory diseases, and overactivation of the IL-17 and IL-22 pathways results in escalation of NCR+ ILC3s in patients with psoriasis." (PMID 37063879, 2023). "Together, these results indicate that intestinal disease-associated Tc17 cells represent a distinct population of inflammatory CD8+ T cells prone to co-produce TNF that can be further functionally subdivided into three subpopulations based on IFN-γ, IL-22 and XCL-1 production." (PMID 35760777, 2022). "It is possible that IL‐22 driven AMP upregulation in the intestine leads to dysbiosis and consequently to intestinal disorders." (PMID 38363052, 2024). "However, excessive amounts of IL‐22 or too little IL‐22 may lead to overexpression or reduced expression of AMPs in the intestine that, as a consequence, trigger microbial dysbiosis possibly leading to intestinal disorders, such as UC and CD." (PMID 38363052, 2024). "Indeed, IL-22, also known as a potent activator of STAT3, is also known as a regulator of intestinal homeostasis and is being developed as a drug for intestinal diseases such as IBD." (PMID 31277507, 2019).
immune diseases (11 papers, 2018 to 2024). "Previous studies have suggested that IL-22 overexpression is associated with immune dysfunction in children with ASD." (PMID 37108638, 2023). "Furthermore, several key genes (e.g., Csf1r, Ifnb1, IL-20, IL-22, IL-24, Jhdm1d, Csf1r, Ifnb1, IL-20, IL-22, IL-24, and Tgfb2 that regulate sex differences in immune diseases) were discovered." (PMID 30246031, 2018). "Interleukin-17 (IL-17) and interleukin-22 (IL-22) act as effector cytokines of the T-helper 17 (Th-17) cells, which play a crucial part to maintain the chronic and relapsing phase of multiple immune diseases that include DED and SS, and were increased in DED patients compared to normal subjects." (PMID 34876936, 2021). "Unlike MUC1, IL-22 also regulates MUC13 expression via p38 MAPK activation, a signaling pathway involved in TLR4-mediated cell proliferation and immune dysfunction in IBD." (PMID 37174625, 2023).
cardiovascular disease (8 papers, 2017 to 2025). "Likewise, increased circulating IL-22 was associated with being male, smoking, lower glomerular filtration rate, T2D, and cardiovascular disease." (PMID 30978932, 2019).
kidney (7 papers, 2017 to 2024). "Our results, suggesting the promotion of OXPHOS and glycolysis by IL‐22 via increasing metabolic regulators expression and glucose uptake, demonstrate that IL‐22 reverses the deteriorating metabolic states associated with the kidney injury." (PMID 33634980, 2021). "Treatment with IL-22 in a murine model of chronic-plus-binge ethanol feeding has shown that IL-22 activates hepatic STAT3 and improves alcoholic fatty liver, liver injury, and hepatic oxidative stress." (PMID 38971765, 2024).